MITF (melanocyte inducing transcription factor)
Diseases named in the same sentence as MITF in open-access papers (continued):
Sharing a sentence is not in itself a finding about the gene and the disease.
melanoma (continued). "This was independent of the BRAF/NRAS mutation status, and suggests that PAX3 induced MITF expression is an inherent melanocyte lineage trait that is conserved in melanoma independently of the genetic background." (PMID 30277012, 2019). "We found that GDF6-activated BMP signaling in melanoma cells represses expression of MITF, a key regulator of melanocyte differentiation, leading to a less differentiated state." (PMID 31868592, 2019). "It has also been reported that in numerous types of cancer, including melanoma, decreased MITF expression is induced by the Wnt/β-catenin pathway." (PMID 31823726, 2019). "Those reversible changes in the percentages of cells expressing MITF indicate a cell variability existing in resistant melanoma cell populations and high capacity of resistance cells to adapt to changes induced by presence or absence of drugs." (PMID 31354817, 2019). "Only one study has reported that miR-101-3p inhibits melanoma proliferation and expansion by regulating MITF in melanoma." (PMID 31412786, 2019). "The majority of DMBC28 cells that survived drug treatment in hyperoxia were MITF-positive and Ki-67-negative, in contrast to drug-treated melanoma cells in normoxia, which were predominantly MITF-negative and Ki-67-positive." (PMID 31461993, 2019). "A similar inquiry into the MALME-3M and MDA-MB-435 human melanoma cells only at the 24 h timepoint following drug addition revealed similar and even more significant increases in GH and MITF levels." (PMID 31547367, 2019). "Based on this MITF rheostat model, the concept of phenotype switch has emerged a few years later to explain the progression of melanoma." (PMID 31118886, 2019). "In melanoma, PGC1A is a direct target of MITF and is known to upregulate mitochondrial biogenesis in melanoma." (PMID 31547367, 2019). "Previous studies have shown that the MITF promoter is potently activated by β-catenin in B16 melanoma cells and melanocytes." (PMID 31823726, 2019). "The immune microenvironment represents a source of resistance to MAPK pathway inhibitors also via an increased number of tumor-associated macrophages, and TNFα and MITF (microphthalmia transcription factor) expression, observed in BRAF-mutant melanomas." (PMID 31652660, 2019). "MITF is essential for melanoma cells and we discovered that BRAF employs a PAX3/BRN2 rheostat to regulate MITF expression." (PMID 30277012, 2019). "In vivo or in 3D culture, MITF and BRN2 are expressed in distinct subpopulations of melanoma cells, likely reflecting a feedback loop in which MITF activates miR-211 expression that represses BRN2 to alleviate the suppression of MITF." (PMID 30804224, 2019). "Using RNAi we confirmed previous findings that both, BRN2 and PAX3 contribute to MITF expression in melanoma cells." (PMID 30277012, 2019). "PGC1α, which mediates mitochondrial biogenesis and respiration, and its driver MITF, are upregulated in HLA-B,C-specific mAb B1.23.2-treated A375-M6 and FO-1β2 melanoma cells." (PMID 31454998, 2019). "MITF is the master regulator of melanocyte development and melanoma formation, as well as proliferation and relapse." (PMID 31604935, 2019). "Activated Notch inhibits MITF function via a competition-based mechanism, thereby triggering the critical transit into the invasive melanoma stage." (PMID 30699982, 2019). "We observed an increase in GH and MITF levels in melanoma cells following treatment with anticancer drugs." (PMID 31547367, 2019). "MITF is downregulated by GDF6-activated BMP signaling to prevent melanocytic differentiation in melanomas." (PMID 31868592, 2019). "To determine if MITF is involved in autophagy regulation in melanoma cells, we performed short-term knockdown of MITF in the human melanoma cell line SkMel28." (PMID 30705290, 2019). "Acute treatment with vemurafenib or trametinib enhanced expression of pigmentation-related genes in MITF-Mhigh melanoma cells, partially as the consequence of transcriptional reprograming." (PMID 31354817, 2019).
melanoma (continued). "The rheostat can also explain why depletion of endogenous BRN2 from different melanoma cell lines can result in different degrees of MITF reduction or even an increase in MITF expression, as reported in 501mel cells." (PMID 30277012, 2019). "We also observed a correlation between IL32 expression, derived from tumor cells and the surrounding microenvironment, and a high AXL/low MITF gene signature, as in the melanoma cell lines." (PMID 30953519, 2019). "Here we show that MITF binds, with high affinity, to promoters of a subset of lysosomal and autophagosomal genes in melanoma cells." (PMID 30705290, 2019). "This suggests that the regulation of MITF expression by the MAPK pathway is highly complex, and multiple factors contribute to the dynamics of MITF levels downstream of ERK in melanoma cells." (PMID 30277012, 2019). "Very low and enhanced levels of DCT expression in drug-treated MITF-Mlow and MITF-Mhigh melanoma cells, respectively, were also confirmed at the protein level by immunoblotting." (PMID 31354817, 2019). "MITF is a ‘lineage-addiction’ or ‘lineage survival’ oncogene in melanoma, amplified in as much as 10% of primary tumors and >20% of metastatic tumors." (PMID 31547367, 2019). "Our results reveal a previously unsuspected role for MITF in metabolism and the network of factors underpinning the hypoxic response in melanoma." (PMID 31207090, 2019). "MITF activity is tightly regulated in melanocytes and melanoma, including transcriptional repression by HIF-1α." (PMID 31461993, 2019). "In fact, NFATc2 targeting reversed melanoma de-differentiation, promoted upregulation of MITF and of melanocyte-lineage-specific antigens, and downregulated the stemness-related marker CD271." (PMID 30710146, 2019). "MLANA and its regulator MITF play a fundamental role in melanocyte development, tumor progression and are overexpressed in melanoma cells." (PMID 31681332, 2019). "Remarkably, proliferative melanoma samples express high levels of MITF (melanocyte inducing transcription factor), SOX10 (SRY-box 10) and PAX3 (paired box 3) genes." (PMID 31383874, 2019). "We observed a correlation between IL32 expression in melanoma tumor biopsies with a high AXL/low MITF drug-resistant signature, consistent with data from melanoma cell lines." (PMID 30953519, 2019). "We have shown that SR-BI in human melanoma is important for the pigmentation phenotype driven by the MITF transcription factor." (PMID 30823658, 2019). "MITF expression correlates with the expression of melanosomal genes in metastatic melanoma samples as well as in a panel of human melanoma cell lines." (PMID 30705290, 2019). "By 30 days after engraftment, we found that dermal melanoma cells had significantly downregulated the expression of Dct and MITF as well as pigmentation." (PMID 31685822, 2019). "It was shown that downregulation of FBXW7 in melanoma leads to increased MITF-mediated dysregulation of oxidative phosphorylation and increased SOX10 mediated migration of melanoma cells." (PMID 31416288, 2019). "In this regard, it has been unclear how melanoma cells with low MITF survive and proliferate in vivo, the majority of which apparently do not exhibit elevated AXL protein expression." (PMID 30651597, 2019). "A recent study showed that debasement of MITF can result in inhibition of the α-MSH-induced cAMP-dependent melanogenesis in melanoma cells." (PMID 30224716, 2018). "Due to its critical role in melanocyte proliferation and differentiation, MITF is considered an important melanoma oncogene." (PMID 30463392, 2018). "Consistent with the ability of Vem to increase pigmentation in cultured melanoma cells and, in some patients’ nevi, the Vem-induced signature was enriched in MITF-targets and in pigmentation genes 25,26." (PMID 30429474, 2018). "We used here the doxycycline (DOX)‐based inducible lentiviral system to stepwise decrease MITF level in six melanoma cell lines." (PMID 29369499, 2018).
melanoma (continued). "The results demonstrate that SEE prevents the activation of the α-MSH−MITF−TYR axis by attenuating Pax3-mediated MITF expression in B16F10 melanoma cells." (PMID 29865165, 2018). "For the first time, it is shown that upon Hsp90i treatment melanoma upregulates MITF expression to sustain CDK2 upregulation to survive, while the MAPK pathway is inactive." (PMID 29507054, 2018). "In line with TFEB, MITF also regulates the expression of PGC1α in retinal pigment epithelium and melanomas, further confirming the role of those transcription factors in energy metabolism." (PMID 29903018, 2018). "Studies show that in addition to regulating melanogenesis, MITF also plays an important role in the regulation of melanocyte development, survival, and tumorigenesis as well as progression of melanoma." (PMID 29755554, 2018). "To exclude the changes occurring upstream of MITF during MITF regulation in vivo, we employed a model whereby MITF expression was inducibly regulated by shRNA in melanoma cell lines." (PMID 29369499, 2018). "Recently, glutamine depletion was shown to be sufficient to engender the decrease in MITF and invasiveness in melanoma cells." (PMID 29369499, 2018). "It has been nevertheless demonstrated that low-MITF melanoma cell lines can also proliferate very fast, implicating sufficient antiapoptotic protection." (PMID 30201866, 2018). "These and other studies indicate the presence of a third subpopulation in melanoma that expresses MITF, AXL, and WNT5A simultaneously." (PMID 29881716, 2018). "A MITF-low subpopulation has been defined in a large-scale RNA-seq analysis of more the 330 melanomas." (PMID 29614062, 2018). "Recently, the expression of the melanocyte-specific markers MITF, MLANA and TYR has been associated with a highly proliferative melanoma cell phenotype that metastasizes to multiple organs." (PMID 30053879, 2018). "A bipolar expression characteristic for the three cell cultures was observed for AXL/MITF signature genes in agreement with recent melanoma single cell transcriptome analyses." (PMID 29614062, 2018). "We found that SA-4 cells also express several genes typical of melanomas, such as MITF, MLANA, S100B, and TYR, which are otherwise poorly expressed in our panel of liposarcoma cell lines." (PMID 29570692, 2018). "Indeed, studies in mice and fish show that melanoma cells switch to a differentiated phenotype at secondary sites, possibly because in melanoma differentiation is closely linked to proliferation through the lineage-specific transcriptional master regulator MITF." (PMID 29545604, 2018). "Amplification of MITF gene was observed in the primary melanoma cell lines (2/8; 25%) at significantly lower level than that observed in metastatic melanoma cell lines (14/24; 58.3%) (p = 0.023; Chi-square)." (PMID 29492214, 2018). "Expression patterns of transcription factors like microphthalmia-associated transcription factor (MITF) and inversely correlated receptor tyrosine kinases like AXL have been implicated in staging of melanoma with respect to progression and resistance." (PMID 29674683, 2018). "To test the growth of established melanoma lines, we chose three low‐MITF and three high‐MITF cell lines and determined their proliferation rate." (PMID 29369499, 2018). "It has been observed that in MITFhigh melanomas, inhibition of MITF increases the efficacy of targeted therapies and delays the acquisition of drug resistance." (PMID 29881716, 2018). "The role of MITF in melanoma is controversial as low MITF/AXL ratio has been related to poor predictive response to targeted therapy in melanoma, while others have reported the involvement of MITF in unresponsiveness to MAPKi and melanoma progression." (PMID 29507054, 2018). "These patterns appear to be relatively common mechanism involved in melanoma progression but with slight modifications, e.g., for MITF/AXL expression and oxphos." (PMID 29614062, 2018).
melanoma (continued). "When studying the phenotypic changes in melanoma, it is crucial to discern the effects of MITF alone from the effects of expression changes in many MITF transcriptional regulators and cofactors that operate upstream of MITF." (PMID 29369499, 2018). "The master regulator of melanoma cell proliferation is the MITF/ZEB-1 couple of transcription factors." (PMID 29973136, 2018). "High MITF concomitantly suppressed activity of RAC1, a kinase mutated in a subset of melanomas 43, and suppression of RAC1 activity was required to reduce invasiveness." (PMID 29369499, 2018). "A moderate MITF level determines the proliferative state of melanoma which is readily targetable with MAPKi." (PMID 29881716, 2018). "It is highly probable that the primary functions of MITF in melanoma are to maintain the lineage identity (by regulating the downstream differentiation markers) and to play the indisputable antiapoptotic role." (PMID 29369499, 2018). "Together, these data indicate that YAP regulates MITF expression in melanoma cells in a PAX3-dependent manner." (PMID 29545604, 2018). "The functional implication of MITF in cancer has been best defined in melanoma, in which the expression of the transcription factor is heterogeneous." (PMID 30310055, 2018). "The three melanoma short-term cultures show common themes of PT dynamics such as a stromal signature at initiation, bipolar expression of the MITF/AXL signature and opposing regulation of poised and activated promoters." (PMID 29614062, 2018). "As pigmented melanomas are of the MITF-high phenotype, the latter is challenging the general belief that it is the MITF-low cell population that is most ‘metastatic’." (PMID 29545604, 2018). "The Xmrk suppresses the differentiation signals relayed by MITF as part of the transformation process leading to melanoma formation in the teleost." (PMID 30544544, 2018). "We demonstrate that collagen stiffness induces melanoma differentiation through a YAP/PAX3/MITF axis and show that in melanoma patients increased collagen abundance correlates with nuclear YAP localization." (PMID 29545604, 2018). "Augmenting MITF levels in melanoma cells should switch the invasive slow-cycling phenotype to a proliferative phenotype." (PMID 29881716, 2018). "In melanoma cells, reduction of the MITF activity has been observed to sensitize the cancer cells to chemotherapeutic agents." (PMID 30157785, 2018). "TYRO3 was identified as a positive regulator of MITF expression in murine melanoma cells and was upregulated in 20 of 40 melanoma cell lines tested relative to other types of human cancer cell lines." (PMID 30501104, 2018). "Low frequency variants conferring moderate risk of melanoma were identified in two genes, MC1R and MITF, which play a key role in melanocyte biology and pigment synthesis regulation." (PMID 29963229, 2018). "Among the different cancer types, melanoma‐derived cell lines exhibited the highest and most significant correlation (Pearson r = 0.8, Padj = 2.4 e−12) between MITF and CDK2 mRNA expression levels (Dataset EV6)." (PMID 29507054, 2018). "Only SOX2, the expression of which was shown to require the Hedgehog signalling in melanoma and is crucial for the self‐renewal and tumorigenicity of human melanoma‐initiating cells 34, sharply increased in three cell lines with induced low MITF." (PMID 29369499, 2018). "Accordingly, premature senescence caused by the knockdown of the melanocyte lineage factor MITF stimulated a SASP, which had the capacity to convey melanoma cells with tumor initiating and metastatic features in a mouse model." (PMID 30237393, 2018). "Overall, our orthogonal analyses point to CDK2 as a candidate whose inhibition overcomes inherent resistance to BRAFi and Hsp90i (driven by MITF) and their combination in melanoma." (PMID 29507054, 2018).
melanoma (continued). "This is most intriguing, as MITF also plays an important role in melanoma, where it is a central regulator of melanoma cell survival, proliferation and differentiation, and as such, considered the marker of the ‘differentiated/proliferative’ phenotype." (PMID 29545604, 2018). "Clinically, primary human melanoma expression microarrays reveals tight linkage between MITF and BCL2." (PMID 30544544, 2018). "As occurs in melanoma, the modulation of MITF expression in PCa cells induces the expression of the cell cycle inhibitor p21 but no changes in the cell cycle inhibitor p16 were observed (data not shown)." (PMID 30310055, 2018). "Reduction of MITF activity sensitizes melanoma cells to chemotherapeutic agents and targeting MITF has been suggested to be a rational therapeutic avenue into highly chemotherapy-resistant melanoma." (PMID 30157785, 2018). "In this context, Jonsson and co-workers have identified a melanoma ‘high-immune signature’, which is significantly correlated with better survival and which intriguingly is characterized by low MITF expression." (PMID 29545604, 2018). "Paraffin-embedded nuclei from 262 melanoma tissue sections were assessed for amplification in all five candidate genes (MITF, EGFR, CCND1, cMET, and cKIT)." (PMID 29492214, 2018). "A MITF-low proliferative group has also been described in a recent survey of different melanoma gene expression studies." (PMID 29614062, 2018). "Both low and extremely high MITF levels give rise to two distinct slow-cycling states of melanoma (e.g., MITFlow/JARID1B-positive and MITFhigh/PGC1α-positive) with increased oxidative phosphorylation that results in treatment resistance." (PMID 29881716, 2018). "The data thus show that even small amounts of MITF are capable of maintaining proliferation of melanoma cells." (PMID 29369499, 2018). "To date, no predictive role for response to therapy has been documented, whereas MITF amplification has been implied on prediction of disease melanoma progression and disease prognosis." (PMID 29492214, 2018). "This is mainly exerted by regulating the level of the master regulator MITF which is the major determinant of the dynamic phenotypic states in melanoma." (PMID 29881716, 2018). "Because the presence of fibroblasts impacted on the MITF signature and as such the melanoma phenotype, we further analysed the communication between melanoma cells and fibroblasts." (PMID 29545604, 2018). "The proliferative and invasive phenotypes of melanoma cells are defined by high and low levels of MITF, respectively, and melanoma cells are capable of switching between these two states, influenced by changing microenvironmental conditions." (PMID 29881716, 2018). "N. sintenisii extracts inhibited cellular melanin biosynthesis and tyrosinase activity in B16F10 murine melanoma cells and decreased MITF level." (PMID 29755554, 2018). "Downregulation of MITF increases the cytotoxic effects of MAPKi on melanoma cells and also reduces the acquisition of drug resistance." (PMID 29881716, 2018). "Based on these experiments with cell lines, we suggest slightly modified model concerning the role of MITF in proliferation and invasiveness of melanoma cells." (PMID 29369499, 2018). "An association was reported between MITF overexpression, partially regulated by AurkA, and MAPK pathway activation in controlling melanoma cell proliferation and migration." (PMID 30218391, 2018). "Opposing AXL/MITF expression in melanoma subsets has gained recent interest, because MITF-low/AXL-high expression signatures were found in tumors of a subgroup of melanoma patients resistant to BRAF/MEK inhibitor treatment." (PMID 29614062, 2018). "Thereby, glucose metabolism controls the expression of the melanoma fate transcription factor MITF, a master regulator of melanoma cell survival and proliferation, invasion and therapy resistance." (PMID 28380427, 2017).